IL6 (interleukin 6)
Diseases named in the same sentence as IL6 in open-access papers (continued):
Sharing a sentence is not in itself a finding about the gene and the disease.
diabetes (continued). "Multivariate joint model results suggested that interleukin-6 had the strongest effect on patient survival, whereas the platelet count was marginal; thrombopoietin and diabetes had no clinically relevant effect, similar to those observed in univariate models." (PMID 35071777, 2022). "Besides, the M1 polarization markers, including IL-1β, IL-6 and TNF-α increased in the isolated retinal microglia from diabetes rats, with the decreasing M2 polarization markers such as IL-4, IL-10 and TGF-β." (PMID 35300330, 2022). "Here, diabetic mice showed activation of NF-κB and increased expression of IL-6 and TNF-α, we found kirenol could inhibit NF-κB activation as well as gene expression of IL-6 and TNF-α induced by diabetes." (PMID 36073930, 2022). "In patients with malnutrition–inflammation–atherosclerosis syndrome and type 2 diabetes, compared to patients with this syndrome but without diabetes, higher levels of leptin (and IL-6 and hs-CRP) and lower HMW adiponectin values were observed." (PMID 36289903, 2022). "Previous studies analyzed the relationship between VF and chronic diseases, including diabetes and CVD, and demonstrated that visceral adipose tissue generates high levels of proinflammatory cytokines, including interleukin-6 and tumor necrosis factor-alpha (TNF-α)." (PMID 36555992, 2022). "Our study addresses this knowledge gap by reporting a consistent and significant association between high baseline IL-6 concentrations and subsequent all-cause mortality in HIV uninfected tuberculosis patients with and without diabetes." (PMID 34711538, 2022). "A 12-week intervention study documented that exercise could decrease the circulation of IL-6 in individuals with type 2 diabetes; 14-week aerobic exercise effectively reduced CRP by 15% among female patients with diabetes." (PMID 36590621, 2022). "Inflammation is the main cause of developing type 2 diabetes mellitus, yet inflammatory markers are rather not specific (i.e. C-Reactive Protein or CRP) or not usually measured in clinic (i.e. interleukin 6 or IL-6)." (PMID 34991564, 2022). "For example, mitochondrial dysfunctions have been unraveled in various autoimmune diseases, such as RA, SLE, and diabetes, while the expression of pro-inflammatory cytokines such as TNF-α, IL-6, and IL-1β is upregulated in the adipose tissues of obese and diabetic subjects." (PMID 35997820, 2022). "IL-6, a potential neurotoxin, was increased in the presence of presumed perinatal infection but not maternal obesity or diabetes." (PMID 35197933, 2022). "The IDEA trial showed similar results in WOMAC scores and reported reduction in inflammation measured by IL-6 levels in an overweight and obese population without diabetes." (PMID 35351093, 2022). "In addition, in a rat diabetes model, exposure to Blautia was positively correlated with inflammatory indicators including, IL-1β, TNF-α, IL-6 and lipopolysaccharides." (PMID 34110438, 2021). "Increased intra-renal FcER1activation in infiltrating mast cells in a patient with diabetes may promote the release of many inflammatory mediators, including TGF-β, TNF-α, IL6, Tryptase, IL1, which can then subsequently drive the development of renal fibrosis." (PMID 34925339, 2021). "In cell and animal models of diabetes as well as in patients with T2DM, elevated levels of circulating and endothelial inflammatory markers, such as interleukin 6 (IL-6) and vascular cell adhesion molecule 1, as well as markers of endothelial dysfunction are generally observed." (PMID 33048256, 2021). "This study showed that the CRP, IL-6, TNF-α levels in saliva were higher in diabetics than healthy controls, supporting the hypothesis that the pathogenesis of type 2 diabetes mellitus involves subclinical chronic inflammation." (PMID 33676486, 2021).
diabetes (continued). "Conversely again, the levels of induction of IL-6, IL-1β, and MCP-1 caused by “diabetes-like” conditions in presence of the non-phosphorylatable (148A) mutant were comparable to those obtained in the absence of HspB4/αA-crystallin (EV)." (PMID 34071438, 2021). "Thus, up-regulation of AGTR1, IL6 and TNFA and reduced production of NO in the context of AGE-RAGE pathway contribute to diabetes and its complications." (PMID 33820928, 2021). "In terms of daily clinical practice, it was stated that increased IL6, IL1 β, and C-reactive protein (CRP) serum levels might precede the onset of type 2 diabetes mellitus, serving as accurate predictors for this condition." (PMID 34207683, 2021). "Diabetes enhances the cytokine response in infections, and studies have shown that people with diabetes had significantly higher levels of IL-6 and other pro-inflammatory cytokines compared to people without diabetes in SARS-CoV-2 infection." (PMID 33801468, 2021). "Twenty obese patients with diabetes (n = 13) and without diabetes (n = 7) underwent assessment of hemoglobin A1c (HbA1c), lipids, IL-6, highly sensitive C-reactive protein (hsCRP), and corneal confocal microscopy before and 12 months after bariatric surgery." (PMID 33475689, 2021). "It seems that diabetic patients diagnosed with SARS-CoV-2 infection had higher values of IL-2, IL-6, IL-10, and interferon gamma than those without diabetes mellitus (NDM) or impaired fasting glucose (IFG)." (PMID 34201473, 2021). "We examined the differences in the levels of zonulin, LBP, β-glucan, sCD14, and IL-6 between hospitalized patients (moderate and severe groups) who had diabetes or not, or patients who had high blood pressure or not." (PMID 34177935, 2021). "Elevated levels of inflammatory markers such as IL-6 and TNF-α were found in RA and correlated with high coronary calcium scores, independent of the Framingham risk score and diabetes." (PMID 34680097, 2021). "During the progression of the disease, all patients with hypertension or diabetes were found to have higher levels of IL-6 compared to patients without these comorbidities." (PMID 33746945, 2021). "A 10-year CVD follow-up study of Caucasian adults reported LAP to be an independent predictor of CVD; the association of LAP with CVD remained significant, even after adjusting for hypertension, diabetes, physical activity, HTG, and pro-inflammatory cytokines (C-reactive protein, IL-6, TNF-α)." (PMID 35010926, 2021). "Ghavimi and colleagues concluded that the frequency distribution of SNP rs1800795 genotypes of IL-6 gene between patients and control group was not significant in 120 people with diabetes and 120 healthy subjects from Isfahan, Iran." (PMID 33767783, 2021). "Inflammatory biomarkers such as IL-6, C-reactive protein, serum ferritin, coagulation index, and D-dimer are increased in patients with diabetes compared with those without diabetes." (PMID 33585030, 2021). "Compared to that at week 1, the levels of IL-6 and IL-8 were significantly elevated at week 2 in non-survivors of diabetic cases, whereas there were greatly reductions in survivors of diabetes at week 2 than at week 1 (P<0.05, respectively)." (PMID 33776910, 2021). "In patients with and without diabetes, metformin has been shown to favorably alter inflammatory mediators, including interleukin 6 (IL-6), TNFα, to possibly boost interleukin 10 (IL-10), and suppress the C-C motif chemokine ligand." (PMID 34367059, 2021). "The other study evaluated an 8-week dose of 6 mg melatonin versus placebo in type 2 diabetes mellitus patients with severe periodontitis and found a reduction in PD, CAL, and serum levels of IL-6 and CRP in the test group along with an increase in serum melatonin levels." (PMID 34066498, 2021).
diabetes (continued). "Since excessive generation of IL-6 and TNF-α compromise insulin sensitivity, suppression of IL-6 and TNF-α by carnosine and histidine can have beneficial effects on reducing or preventing diabetes-related complications as well as preventing altered endothelial function by inflammation." (PMID 34203479, 2021). "Diabetes and hypertension lead to structural and functional changes of the neurovascular unit, alter collaterals, and elevate MMP-9, ROS, and proinflammatory cytokines (TNF, IL-1β, and IL-6)." (PMID 34054705, 2021). "Anti-IL-6 (0.01 mg/kg b.wt., for 5 days) or anti-IL-17A (0.1 mg/kg b.wt., for 5 days) were administered to IDDM rats within 1 day after diabetes manifestation (blood glucose > 7.5 mmol/l), either alone or in combination with anti-TCR (0.5 mg/kg b.wt., for 5 days) in a double or triple fashion." (PMID 32106855, 2020). "The presence of Porphyromonas gingivalis in the periodontal pockets affects the glycemic index in diabetes, and the periodontitis-inducing cytokines TNF-α, IL-6 and IL-1β are also insulin antagonists, triggering irreversible changes in the body's immune response and inflammatory state." (PMID 32634783, 2020). "Interleukin-6 (IL-6) level was found to be higher in SARS-CoV-2 cases with diabetes than those without diabetes." (PMID 32527756, 2020). "This study shows that locally applied vitamin C reduces alveolar bone and attachment loss, decreases levels of CTX in serum and it also reduces AGE, IL-6, 8-OHdG, and MMP-8 immunostaining in gingival tissue in rats with experimentally induced periodontitis and diabetes." (PMID 33263670, 2020). "The elevated circulating level of IL-6 is an independent predictor of T2DM, patients with T2DM have significantly higher level of IL-6 compared than those without diabetes." (PMID 33016995, 2020). "However, animal study suggests that HIF-1α still regulates IL-6 expression in diabetic retina as increased HIF-1α, IL-6, and TNF-α are found in diabetic retina of diabetic rats, which can be decreased by the HIF-1α inhibitor." (PMID 33013692, 2020). "Within only those without diabetes (n=37) the mean IL-6 concentration (back transformed) at baseline was 6.4 pg/ml (SD 12.1) in those that went onto heal compared with 90 pg/ml (SD 243.1) in those who did not (p<0.01)." (PMID 34104801, 2020). "Studies have demonstrated that activation of neutrophils and macrophage results to oxidative stress as well as inflammatory cytokines release including IL-1β, IL-6 and TNF-α, leading to the decrease of insulin secretion, hepatic steatosis and a series of metabolic disorders in diabetes." (PMID 32028957, 2020). "Diabetes, impaired fasting glucose, HbA1c, hypertension, male sex, BMI, cTnT, CACS, WBC count, the number of all leukocyte types analyzed, and the levels of CRP, IL‐6, and TNF‐α were reproducibly, positively correlated with the QRS‐T angles." (PMID 32638456, 2020). "However, diabetes patients showed higher neutrophil counts, higher CRP, IgE, and IL-6, TNF and IFN-γ levels." (PMID 33584667, 2020). "Decreased GSK3β-Ser9 phosphorylation, increased TNF, IL-6, COX-2, and iNOS expression, and the abolishment of these effects by SB216763 can also be observed in the hippocampi of rats with diabetes induced by a combination of a high-fat diet and low streptozotocin concentrations." (PMID 32231133, 2020). "Quercetin treated normal rats also showed higher IL-6 and TNF-α levels compared to diabetic rats, implying that quercetin may play an effective role in regulating metabolism in diabetes." (PMID 32694996, 2020). "Also, some of these biomarkers like hs-CRP, IL-6, and TNF-α have direct value on diabetes incidence prediction." (PMID 31901246, 2020). "The increase in IL-6 and TNF-α observed in diabetes state also acts as antierythropoietic factors expressed in the present study by the decrease in erythrocytes count, hematocrit, and mean corpuscular of haemoglobin values, which are some conventional signs of anemia." (PMID 33293987, 2020).
diabetes (continued). "Last, the crosstalk between myokines (e.g., interleukin-6, irisin, and fibroblast growth factor 21) and adipokines (e.g., adiponectin, adipocyte fatty acid-binding protein) is thought to contribute to SMFD in diabetes." (PMID 32630360, 2020). "Mean concentration levels of ANG-2, IL-6, miR-126 and miR-146a were higher in those with diabetes than for those without." (PMID 34104801, 2020). "In analogy with the finding that high IL-6 upregulates MSTN in muscle, diabetes-induced low grade inflammation might upregulate MSTN in circulating cells." (PMID 32286342, 2020). "Ablation of neuronal Pdk2 in the hypothalamus did not alter diabetes-induced expression levels of Tnf-α, Il-1β, and Il-6 mRNA, or gliosis." (PMID 33219201, 2020). "This explains the significantly raised serum IL-6 levels in acromegaly patients with diabetes as compared to without diabetes in our study." (PMID 33154456, 2020). "Compared with the non-diabetic group, patients with diabetes had elevated levels of inflammatory markers, including IL-6 and high-sensitivity C-reactive protein (hs-CRP), and decreased adiponectin levels." (PMID 32015418, 2020). "In addition, increased levels of inflammatory cytokines, such as interleukin (IL)-1, IL-6, and tumor necrosis factor alpha (TNF-α), are observed in diabetes but are also found in AD patients." (PMID 30845785, 2019). "Studies using the inflammatory cytokines interleukin-6 (IL-6) C-reactive protein, and tumor-necrosing-factor alfa (TNF-α) have shown that regardless of the presence of diabetes these markers are associated with the occurrence of microalbuminuria and mortality." (PMID 30997790, 2019). "A statistically significantly negative correlation between durations of diabetes and pSTAT3 expression [baseline, unstimulated expression and IL-6 stimulation] was found." (PMID 31286987, 2019). "T2DM patients with CV disease had, as compared to those without CV disease, higher IL-6 and cfPWV, after adjustment for sex, age, BP, smoking habit, diabetes duration, BP-lowering, lipid-lowering and diabetic treatment." (PMID 31077210, 2019). "The exact mechanism of interplay between IL-6, STAT3, and SOCS3 at an organismal level during diabetes is likely complex; thus, it was of interest to determine if hyperglycemia itself might mediate altered IL-6R function in keratinocyte culture." (PMID 31073533, 2019). "Dyslipidemia rates between the high and low IFN-γ groups and the rates of diabetes mellitus between the high and low IL-6 groups (P = 0.5327 and P = 0.0635, respectively) were not significantly different." (PMID 30611204, 2019). "As expected, patients with high CAC (> 100 AUs) were older, higher prevalence of clinical CVD and diabetes, had higher levels of systolic BP, hsCRP, TNF, IL-6 and, lower levels of triglycerides, creatinine, serum albumin, total testosterone in male,and T-score of tBMD." (PMID 30777028, 2019). "Taken together, we considered that diabetes might increase the level of TNF-α and IL-6 and trigger the degradation of tight junction and the disruption of BBB in the brain, which eventually caused cognitive impairment." (PMID 29867440, 2018). "Indeed, HSP60 levels were increased in the diabetes group together with an increase in HSP72 levels, whereas clear decreases in IL-6 and TNF-α levels were noted in this group." (PMID 29467719, 2018). "Interestingly, with ANOVA analysis, the exercise significantly increased circulating inflammatory markers (IL-1β, IL-6, TNF-α, and IL-10) and decreased WBC, while diabetes displayed significant effect on HR and TNF-α." (PMID 29467719, 2018). "Along these lines, incident diabetes in HIV+ individuals on ART has been associated with increased levels of circulating inflammatory markers, independent of BMI, including hsCRP, IL-6, and TNFR1 and TNFR2 levels." (PMID 29795574, 2018).
diabetes (continued). "Diabetes accompanied by inflammation and heart disorder is correlated with increased inflammatory biomarkers and cytokines, and therefore, plasma E-selectin, CRP, and IL-6 can be augmented in diabetic rats." (PMID 30510626, 2018). "In the univariate model, diabetes, FTO rs3751812, and IL-6 rs1800796 were associated with neither OS nor PFS of breast cancer patients (all P values > 0.05), while HSPD1 rs2605039 was significantly associated with PFS (P = 0.031) but not OS (P = 0.061)." (PMID 28591216, 2017). "The pathophysiological link between COPD and diabetes is not entirely understood, although thought to involve systemic inflammation with central roles for IL-6 and TNF-α." (PMID 29165119, 2017). "Macrophages, by the release of proinflammatory cytokines (e.g., TNF-α, IL-6, and IL-1β), aggravate inflammation, which may be explained by the increased GLU activity in the STZ-induced diabetes." (PMID 29464184, 2017). "In contrast, IL-6 and PAI-1 are directly related to diabetes mellitus." (PMID 28878683, 2017). "Interleukin-6 (IL-6), another pro-inflammatory cytokine released by adipocytes, in turn induces a rise in C-reactive protein (CRP) from the liver; elevated levels of these inflammatory markers have been shown to predict the onset of diabetes." (PMID 28817063, 2017). "Several authors have found significantly increased intraocular concentrations of proinflammatory interleukins IL-6, IL-8, and IL-12 in patients with diabetes compared with patients without diabetes." (PMID 28252875, 2017). "Therefore, we believe the presence of comorbid diseases, such as diabetes, hypertension and dyslipidemia, elevate CRP and IL-6 levels and contribute to sarcopenia." (PMID 28851881, 2017). "Moreover, the anti-inflammatory action of melatonin was demonstrated by a significant decrease in cytokines IL-1β, IL-6 and PGE2 in gingival crevicular fluid of patients with diabetes and periodontal disease." (PMID 29075409, 2017). "We hypothesized that abnormal IL-6 mRNA expression, macrophage activation, and p38 MAPK and PI3K/Akt signaling contribute to impaired wound healing in diabetes." (PMID 28542434, 2017). "Thus, PGE2-EP4 has similar effects in vitro and in vivo on IL-6 and TNF-α in diabetic mice, and the effects of diabetes on Il6 and Tnfa are dependent on myeloid cell EP4." (PMID 27351842, 2016). "Only in patients suffering from diabetes with critical ischemia of the lower extremities, the concentration of IL-6 proved to be higher than in such patients without diabetes." (PMID 27834825, 2016). "However, one month later western blotting analysis showed an increase in the amount of immunoreactive peptide for IL-1β, IL-6, and TGF-β1 in plasma of groups with diabetes (resp)." (PMID 26955430, 2016). "Not just act as a clinical marker, IL-6 has been shown to be deeply involved in the pathogenesis of cardiac diseases and cardiovascular complications of diabetes." (PMID 26972749, 2016). "A previous study demonstrated that both inflammation and oxidative stress are involved in the process of I/R injury in an experimental model of diabetes and increased pro-inflammatory cytokines including TNF-α and IL-6 were observed at early stages in transient global ischemia." (PMID 26982373, 2016). "Serum magnesium levels are also negatively correlated with levels of CRP and IL-6 in patients with and without diabetes." (PMID 27547762, 2016). "The concentrations of E-selectin and CRP in the blood serum were higher, and the concentrations of IL-6 and fibrinogen were lower in patients suffering from controlled type 2 diabetes than in patients without diabetes." (PMID 27834825, 2016). "Moreover, in patients suffering from both diabetes and PAD, there was a correlation between the concentration of IL-6 and the concentrations of CRP and fibrinogen, which was consistent with the results we obtained for patients suffering from diabetes." (PMID 27834825, 2016).